PHLDA3 (pleckstrin homology like domain family A member 3)
Diseases named in the same sentence as PHLDA3 in open-access papers (continued):
Sharing a sentence is not in itself a finding about the gene and the disease.
cancer (20 papers, 2009 to 2025). A tumor composed of atypical neoplastic, often pleomorphic cells that invade other tissues. "Loss of PHLDA3 expression is linked to poor prognosis across various cancers, including NETs and SCCs." (PMID 40227573, 2025). "This correlation suggests that functional loss of PHLDA3 can contribute to AKT activation in LNET development in these specific cancers." (PMID 40227573, 2025). "We conducted a comprehensive analysis using the R2 platform to detect genes associated with PHLDA1, PHLDA2, and PHLDA3 expression in particular cancers." (PMID 38921000, 2024). "In contrast to PHLDA2, we discovered 85 genes (referred to as the “PHLDA3-centered positive cluster”) that were positively linked with PHLDA3 and were present in every component of cancer set A." (PMID 38921000, 2024). "Further, PHLDA3 has been linked to a variety of cancers, including lung endocrine cancers, pancreatic neuroendocrine cancers, primary breast cancers, and prostate carcinomas, based on the traits of its tumorigenesis-related cell activities." (PMID 38921000, 2024). "There is an association between PHLDA3 expression levels and cancer patient survival." (PMID 40227573, 2025). "In these lung NETs, PHLDA3 gene expression was lower and Akt activation was higher compared to normal tissues, raising the possibility that loss of PHLDA3 function caused Akt activation in these cancers." (PMID 32521808, 2020). "Collectively, these results illustrate the multifaceted roles of PHLDA3 protein in modulating the Wnt signaling pathway across different types of cancer." (PMID 40227573, 2025). "This review explores the complex interactions between PHLDA3 and key cellular processes involved in cancer, emphasizing its regulatory mechanisms and clinical relevance." (PMID 40227573, 2025). "This review underscores the pivotal role of PHLDA3 in cancer progression, particularly in EMT, invasion, and metastasis." (PMID 40227573, 2025). "This makes PHLDA3 a valuable prognostic marker, and its role in suppressing cancer progression highlights its potential as a promising therapeutic target." (PMID 40227573, 2025). "In summary, PHLDA3 plays a significant role in suppressing tumors across various cancer types, impacting key signaling pathways and cellular processes involved in cancer progression." (PMID 40227573, 2025). "This review provides a detailed analysis of the role of PHLDA3 in cancer progression, including metastasis and invasion, underscoring its therapeutic potential." (PMID 40227573, 2025). "Given its regulatory role, PHLDA3 can be used as a prognostic marker and therapeutic target in many cancers." (PMID 40227573, 2025). "Collectively, these results demonstrate that PHLDA3 plays a significant role in cancer progression and patient prognosis across various cancers." (PMID 40227573, 2025). "This review provides a comprehensive understanding of PHLDA3’s complex involvement in cancer progression, including metastasis and invasion, highlighting its therapeutic implications for advanced-stage malignancies." (PMID 40227573, 2025). "Our multiomics research showed that PHLDA1, PHLDA2, and PHLDA3 have various functions in the development of cancer and regulate the prognosis of patient’s cancer differently." (PMID 38921000, 2024). "Based on information from the PrognoScan database, the predictive significance of PHLDA1, PHLDA2, and PHLDA3 expression levels for various cancer patients was also evaluated." (PMID 38921000, 2024). "Using the cBioPortal, we independently analyzed the genetic changes in PHLDA1, PHLDA2, and PHLDA3 in distinct cancer types and then provided a comparative report regarding the functional protein partners of glutaminases obtained using PPI network analysis." (PMID 38921000, 2024). "Since these pleckstrins are highly expressed in some cancers, the R2 genomics platform was utilized to find genes associated with PHLDA1, PHLDA2, and PHLDA3." (PMID 38921000, 2024).
cancer (continued). "In contrast, CDKN1A has positive co-dependency with PHLDA3, another factor involved in the intrinsic apoptotic pathway and RAP2B, which is implicated in proliferation and migration of cancer cells." (PMID 36681780, 2023). "Among these genes Phlda3 is a well-known radiation response gene in both normal human and cancer cells and a known target of p5347." (PMID 35986207, 2022). "Pleckstrin homology-like domain family A, member 3 (PHLDA3), is emerging as a critical regulator for multiple cancers." (PMID 35112982, 2022). "PPP metabolites, in turn, reinforce AKT activation and further promote cancer metabolic reprogramming by blocking the expression of the AKT inhibitor PHLDA3." (PMID 32312982, 2020). "Insights gained from an understanding of the role of PHLDA3 could pave the way for developing novel treatments and improving therapeutic strategies against these aggressive cancers." (PMID 40227573, 2025). "Recent research underscores PHLDA3’s significant role in various cancers." (PMID 40227573, 2025). "According to these findings, PHLDA1, PHLDA2, and PHLDA3 may partially co-express to control the prognosis of cancer." (PMID 38921000, 2024). "Our study of the underlying mechanism of cancer prognosis concerning pleckstrin expression may be aided by the finding that the patterns of PHLDA1, PHLDA2, and PHLDA3 co-expression regulated the clinical outcomes of individuals with certain types of cancer." (PMID 38921000, 2024). "For PHLDA3, positively correlated genes were detected in gastric, kidney, lung, and cholangiocarcinoma cancer, respectively, and 85 genes were found to be common in all cancers." (PMID 38921000, 2024). "Therefore, it is difficult at this moment to predict the percentages of cancer patients with PTEN null/PHLDA3 vs. PTEN null/PHLDA3 KO genotypes." (PMID 32312982, 2020). "We also demonstrated that the effects of PPP inhibition on AKT activation and cell proliferation are PHLDA3-dependent and predict that the PHLDA3 status in human cancers may dictate their response to anti-PPP treatments." (PMID 32312982, 2020). "The negative regulators in these crosstalk mechanisms, such as TRIM21 and PHLDA3 discovered in this study, may contribute to cancer development and treatment resistance." (PMID 32312982, 2020). "Since PHLDA3 regulates the PI3K/Akt/mTOR pathway by suppressing Akt activation, it is possible that new drugs that mimic PHLDA3 function may show efficacy not only in PanNETs but also in other cancers in which Akt is highly activated." (PMID 32521808, 2020). "Furthermore, molecules simulating PHLDA3-mediated inhibition could also be efficient in other cancers presenting Akt activation." (PMID 34638668, 2021). "Therefore, it would be of great interest to ask if PHLDA3 function is defective in these cancers." (PMID 32521808, 2020). "However, PTEN and PI3K/AKT status cannot be tracked from this study, nor from other PHLDA3-associated human cancer studies." (PMID 32312982, 2020). "Since PHLDA3 regulates AKT through inhibition of its signaling pathway, it can influence AKT-mediated processes in cancer progression." (PMID 40227573, 2025).
cancer (continued). "Recently, several reports indicated that pleckstrin homology-like domain family A member 3 (PHLDA3) functions as an AKT inhibitor and plays a crucial role in the cell fate of cancer cells." (PMID 35203369, 2022). "We found that in the Pten null mES and in vivo cancer models, the abundant PPP metabolites can restrain PHLDA3 expression, which in turn activates AKT and further promotes cell growth." (PMID 32312982, 2020). "Since carcinomas and abnormal findings were not confirmed in the liver, RT-qPCR was performed to examine the expression levels of Glipr1, Clec12a, and Phlda3 in 3-, 6-, 12-, 24-, and 32–34-month-old mouse livers." (PMID 37648885, 2023). "In addition, the cancer tissues of 12 PAAD patients were stained with the HPA027601 antibody, and the results showed that the PHLDA3 indicators were positive in all of the 12 tissue samples." (PMID 36142223, 2022). "However, considering the characteristics of SP cells for cancer-initiating ability, the apoptosis-related molecules among these genes (MCL-1, ANKRD11, PHLDA3 and APOL1) might have roles in the proliferation of SP cells." (PMID 19826427, 2009).
lung (1 paper, 2020).
PHLDA3 also shares sentences with these, for which no sentence is quoted: breast carcinoma (1 paper); cancers of the stomach (1); hematologic malignancies (1); kidney cancer (1); lymph node metastasis (1); neurodegenerative disease (1); preeclampsia (1); psychosis (1); renal carcinoma (1); testicular cancer (1); uterine cancer (1).